KDM5C (lysine demethylase 5C)
Diseases named in the same sentence as KDM5C in open-access papers (continued):
Sharing a sentence is not in itself a finding about the gene and the disease.
tumor (continued). "In ccRCC, KDM5C mutations are found at increased frequency in sub-clones within primary tumours as well as in metastases, in comparison to single biopsies of primary tumours, indicating that they arise later during the process of ccRCC evolution rather than being truncal mutations." (PMID 39955388, 2025). "Therefore, we speculated that the suppression of tumor growth and metastasis of KDM5C may be associated with fatty acid metabolic pathway." (PMID 32714863, 2020). "In conclusion, SIX5 functions as a critical oncogenic driver in GBM, regulated by KDM5C and promoting tumor progression through UBE2C-mediated activation of AKT/mTOR signaling and glycolytic reprogramming." (PMID 41939887, 2026). "Mutations in KDM5C that occur across all tumour types, including in ccRCC, papillary RCC and chromophobe RCC tumours show the typical pattern of inactivation of a tumour suppressor gene, being present throughout the coding region." (PMID 39955388, 2025). "Inactivation of KDM5C or KDM6A through deletion or mutation leads to epigenetic changes in the targeted transcription factor circuitry, disrupting tumor differentiation and promoting tumor cell proliferation." (PMID 41301905, 2025). "Future studies will incorporate functional assays using BTC-derived organoids and CRISPR-based editing to determine how KDM4B, KDM5C, and KDM6A mutations contribute to epigenetic dysregulation and tumor initiation." (PMID 41301905, 2025). "KDM5C was considered a tumor suppressor in different cancers such as BC, clear cell renal carcinoma, and cervical cancer by regulating enhancer function." (PMID 38769556, 2024). "The stimulatory effect of YY1 on tumor cell growth was at least partially dependent on the presence of KDM5C." (PMID 39433896, 2024). "Several studies have indicated that KDM5C is involved in regulating different biological processes in tumor cells through its histone demethylase activity and functions as a tumor suppressor." (PMID 39433896, 2024). "The histone demethylase KDM5C has been identified as playing a role in both tumor promotion and suppression depending on the specific tumor contexts and targets involved." (PMID 38216914, 2024). "As a specific H3K4 histone demethylase, KDM5C plays dual roles as both a proto-oncogene and tumor suppressor." (PMID 39433896, 2024). "By shRNA-mediated knockdown of Kdm5c/KDM5C, we demonstrated tumor-suppressive properties in murine and human AML models, whereas we observed no advantageous effects in normal murine hematopoietic cells." (PMID 36631623, 2023). "Supporting a tumor suppressive function, Kdm5c-KD resulted in a profound enrichment (19-32 fold) of cells expressing Kdm5c-targeting shRNAs compared to control AML cells." (PMID 36631623, 2023). "In contrast, our data demonstrate a broader tumor suppressive function of KDM5C suggesting significant redundancy between KDM5 family members." (PMID 36631623, 2023). "Using this set-up, we identified KDM5C, a H3K4me2/me3 demethylase, as a tumor suppressor in AML and further validated its function in cell lines and primary human AML." (PMID 36631623, 2023). "Mechanistically, KDM5C exerted effects on tumor development by reducing H3K4me3 at specific promoters and downregulating its target gene fatty acid synthase (FASN)." (PMID 37185761, 2023). "In contrast, knock-down of KDM5C resulted in an attenuated xenograft tumor growth and smaller tumor volumes." (PMID 37202737, 2023). "Previous studies indicated that KDM5C predicted higher tumor immunogenicity and inflamed anti-tumor immunity alterations." (PMID 37202737, 2023). "The list of potential tumor suppressor hits included both known factors, such as Ezh2 and Tle4, as well as novel candidates, including Kdm5c, Pcgf3, Chd1 and Pbrm1." (PMID 36631623, 2023). "Aiming to identify novel epigenetic regulators in AML, we performed an shRNA-screen using a murine model of CEBPA mutant AML and identified KDM5C as a novel tumor suppressor." (PMID 36631623, 2023).
tumor (continued). "As the expression data from healthy controls for GBM are missing in TCGA, we used RNA-Seq data from post-mortem brains in GTeX to verify that KDM5C is indeed overexpressed in tumor samples." (PMID 36142158, 2022). "In the subtype analysis, CPCS2 had a higher tumor mutation burden than CPCS1, such as mutation of KDM5C, PTEN and XIRP." (PMID 36581992, 2022). "The role of KDM5C in cancer is still controversial, given the dual -pro-oncogenic and suppressive properties, which are highly tumor-specific." (PMID 36142158, 2022). "It has been firmly established that KDM5C has dual roles as both a tumor suppressor and an oncogene." (PMID 36550096, 2022). "The expression of TRIM11 and KDM5C in all tested tumor tissues was correlated, and the p value was very close to the significant value (p = 0.055)." (PMID 36192394, 2022). "It has been shown that the overexpression of KDM5C suppresses tumorigenesis, whereas the depletion of KDM5C has been shown to enhance tumor growth in vitro and in mouse xenograft models." (PMID 35805040, 2022). "KDM5C is mainly located in the nuclei of normal tissue cells, and is much lower in the nuclei of tumor cells." (PMID 36192394, 2022). "KDM5C expression was increased in the invasive tumor front whereas E-cadherin expression was reduced in this region." (PMID 35454801, 2022). "KDM5C is one important tumor-suppressive regulator for oncogenic enhancers, but its regulatory mechanisms still remain elusive." (PMID 36192394, 2022). "The result showed that TRIM11 mainly increased in nuclei, and KDM5C was high in the nuclei of normal tissue cells and low in the nuclei of tumor tissue cells." (PMID 36192394, 2022). "Inactivating mutations in ccRCC are also found in two histone demethylases known to be tumour suppressors: KDM5C (demethylates H3K4me3) and KDM6A /UTX." (PMID 35406676, 2022). "The results showed that TRIM11 knockdown greatly reduced the volume and weight of tumors, and KDM5C knockdown increased tumor growth." (PMID 36192394, 2022). "The growth of tumors with PC3 xenografts was significantly faster than the tumor growth of KDM5C knockdown cell xenografts over the course of 29 days." (PMID 35454801, 2022). "Tumor volume was dramatically induced after mice were estrogen‐treated for four weeks, which was significantly attenuated when KDM5C was knocked down." (PMID 33977073, 2021). "Mechanistically, KDM5C altered tumors was found to be markedly correlated with enhanced tumor immunogenicity and immunosupportive features of anti-tumor microenvironment." (PMID 33953726, 2021). "Lysine (K)-specific demethylase 5C (KDM5C) plays a significant role in the tumor cell proliferation, invasion, drug resistance and the regulation of tumor-related gene expression." (PMID 33953726, 2021). "KDM5C was reported to be a tumor suppressor in ccRCC since knockout of KDM5C in ccRCC promoted the expression of several HIF1α-responsive genes and tumorigenesis." (PMID 34522206, 2021). "It was found that KDM5C KD led to a significant reduction of tumor volume, strengthening the oncogenic role of KDM5C in breast tumorigenesis." (PMID 33977073, 2021). "In conclusion, KDM5C alterations was correlated with enhanced tumor immunogenicity and inflamed anti-tumor immunity, thus resulting in better treatment outcome in cancer patients receiving ICIs." (PMID 33953726, 2021). "Overall, the frequency distribution of somatic mutations detected in our cohort is comparable to large-scale studies of primary tumours with VHL (40.5%), PBRM1 (40.5%), and KDM5C (32.9%) being the most frequently mutated genes in our cohort." (PMID 34944839, 2021).
tumor (continued). "One study has shown that six of such genes show increased loss-of-function mutations in male tumor diseases (ATRX, CNKSR2, DDX3X, KDM5C, KDM6A, and MAGEC3)." (PMID 32629877, 2020). "In conclusion, our results suggested that KDM5C efficiently represses cell proliferation and invasion and exerts tumor-suppressing activity in ICC cells." (PMID 32714863, 2020). "In this research, we verified that KDM5C has a novel tumor-suppressing role in ICC, which inhibits the proliferation of invasion of ICC cells both in vitro and in vivo." (PMID 32714863, 2020). "Critically, the tumor sizes of the xenografts were significantly smaller in KDM5C-overexpressed group than control." (PMID 32714863, 2020). "We only found significant correlations between KDM5C expression and regional lymph node metastasis (p = 0.009), and tumor-node-metastasis stage of ICC (p = 0.013)." (PMID 32714863, 2020). "Studies on oncometabolite have shown that the KDM5C is involved in cancer-related metabolic reprogramming and the tumor suppression." (PMID 33324444, 2020). "We have reviewed the most recent findings regarding cancer-specific metabolic reprogramming and the tumor-suppressive roles of JARID1C/KDM5C and UTX/KDM6A." (PMID 31221981, 2019). "Its inhibitory effect on tumor growth can be relieved by the loss of PBRM1, KDM5C, SETD2 or BAP1 to promote robust tumor growth." (PMID 30355451, 2018). "Significant correlations were found between KDM5C expression and tumor diameter, microvascular invasion, and tumor differentiation." (PMID 26503415, 2015). "In conclusion, we found that KDM5C expression was generally higher in HCC lesions compared with non-tumor tissues." (PMID 26503415, 2015). "They discovered convergent tumor evolution since a given tumor contained different mutations of the same genes, SETD2, KDM5C and PTEN, depending on its spatial orientation." (PMID 25411563, 2014). "Based on the mutations' prevalence we estimated that three different tumor regions should be sampled to detect mutations in PBRM1, SETD2, BAP1, and/or KDM5C with 90% certainty." (PMID 25124064, 2014). "In our cohort, we estimated that a minimum of three tumor regions must be sampled to detect mutations in PBRM1, SETD2, BAP1, and/or KDM5C with 90% certainty." (PMID 25124064, 2014). "Strikingly however, KDM5D mutant cells failed to form xenograft tumours but the combination of KDM5C and KDM5D mutations restored the ability to form tumours." (PMID 39955388, 2025). "Considering these findings, we propose the following model: YY1 chromatin recruitment is at least partially dependent on the presence of KDM5C, and in tumor cells with high KDM5C expression, a small amount of YY1 can be recruited to chromatin even after KDM5C is knocked down." (PMID 39433896, 2024). "In conclusion, this study compelling evidence establishing KDM5C as a tumor promoter in CRC." (PMID 38216914, 2024). "Most evidence supports that KDM5A/B is a carcinogenic factor in BC, while KDM5C may have tumor suppressive functions." (PMID 38769556, 2024). "Importantly, targeting YY1 effectively inhibited the proliferation and tumorigenicity of tumor cells with low KDM5C expression." (PMID 39433896, 2024). "Similarly, the tumor weight was significantly reduced when KDM5C was silenced but enhanced when PFDN5 was further knocked down." (PMID 38216914, 2024). "The tumor promoting role of KDM5C has been observed as well." (PMID 38216914, 2024). "In addition, tumor cell proliferation was markedly inhibited only when both of KDM5C and YY1 were depleted in the KDM5C-proficient tumor cells ACHN and 769-P (H and EV1B)." (PMID 39433896, 2024). "Given the involvement of WNT in tumorigenesis, our data may have additional implications for cancer research, particularly considering the role of KDM5C as a tumour suppressor in certain cancers." (PMID 38383780, 2024).
tumor (continued). "Furthermore, we found that KDM5C levels predicts outcome in female AML patients thus identifying KDM5C as a female-biased tumor suppressor in AML." (PMID 36631623, 2023). "Collectively, these results confirm a tumor suppressive role for KDM5C in AML." (PMID 36631623, 2023). "Finally, the association of KDM5C levels with long-term disease-free survival of female AML patients emphasizes the clinical relevance of our findings and identifies KDM5C as a novel female-biased tumor suppressor in AML." (PMID 36631623, 2023). "Of note, the tumour suppressors KDM5C and KDM6A have been previously identified to play fundamental roles in cancer sex-disparity, as they escape XCI to retain their function when mutated, while ZRSR2 mutations/loss have been associated with sex-disparity in blood cancers." (PMID 37759468, 2023). "Interestingly, KDM5C, or JARID1C/SMCX, plays a dual role in different tissues; it is pro-carcinogenic in breast epithelial cells and conversely tumor suppressive in kidney cells." (PMID 37880235, 2023). "Overexpression of KDM5C led to accelerated xenograft tumor growth and larger tumor volumes." (PMID 37202737, 2023). "Silencing of KDM5C in bone metastatic PCa cell line PC3 inhibited tumor growth in mouse xenografts." (PMID 35454801, 2022). "We also observed relatively high KDM5C signal in the cytoplasm of tumor cells." (PMID 36192394, 2022). "Interestingly, we found a co-overexpression of KDM5C and the tumor prognostic genes HIF1A, p75 and survivin (alias BIRC5), involved in hypoxia-mediated mechanisms, as aggressiveness and a poor therapeutic response." (PMID 36142158, 2022). "Considering the debated role of KDM5C as an oncogene or tumor suppressor and its crucial contribution in brain functioning, we first aimed to establish KDM5C expression levels by real time PCR (RT-PCR) in tumor samples (N = 37) derived from GBM patients compared to brain control samples (N = 8)." (PMID 36142158, 2022). "It is probably that TRIM11 degrades KDM5C in the nuclei of tumor cells." (PMID 36192394, 2022). "Mouse xenografts of KDM5C knockdown cells showed reduced tumor growth." (PMID 35454801, 2022). "The predominantly metastatic tumours in our cohort contained more frequent mutations in several genes such as SETD2, APC, KDM5C, HIF1A, RBM10, TRAK1 and FBXW7, while we detected lower mutation rates in VHL compared to the primary tumours analysed in the TCGA study." (PMID 35231161, 2022). "KDM5C knockdown also leads to reduced tumor growth in in vivo mouse xenografts." (PMID 35454801, 2022). "Related to this consideration, our molecular study in the 5-ALA FGS tumor samples revealed a peculiar expression profile across the microenvironmental cells residing in different tumor niches with a higher expression of the stem cell markers in the tumor core and of KDM5C in the tumor rim." (PMID 36142158, 2022). "In addition, a group of tumor suppressors that escape from X-inactivation have been implicated in cancer sex bias 30, our analysis did reveal higher expression of ATRX, DDX3X, KDM5C and KDM6A in female than male patients." (PMID 36118521, 2022). "So far, the tumor-suppressive roles of KDM5C have been most studied in ccRCC." (PMID 35805040, 2022). "In contrast, KDM5C functions as an oncoprotein or tumor suppressor in a context-dependent manner." (PMID 35805040, 2022). "Double immunofluorescence staining from the tumor tissue demonstrated that depletion of either SF3A3 or KDM5C showed significantly reduced fluorescence intensity compared to control cells while this decrease was enhanced by deletion of both SF3A3 and KDM5C, simultaneously." (PMID 35248043, 2022). "Our in vitro and in vivo data indicated that the epigenetic factor KDM5C, as a tumor suppressor, was a novel metabolic regulator, and its absence caused ccRCC-specific metabolic phenotypes, thus providing a direct link between epigenetic abnormalities and cancer metabolism." (PMID 34522206, 2021).
tumor (continued). "To test whether KDM5C affects tumor growth in vivo, we injected nude mice subcutaneously with control MCF7 cells or MCF7 cells with KDM5C KD, and then treated with or without estrogen." (PMID 33977073, 2021). "For example, the interaction between ZMYND8 and PKCβ or TROJAN may induce pro-oncogenic effects, while interaction between ZMYND8 and KDM5C, KDM5D, or ZNF592 may cause tumor-suppressive effects." (PMID 33670804, 2021). "KDM5C was reported to display a dual role as both an oncogene and a tumor suppressor." (PMID 32714863, 2020). "Well-defined tumor margins, nodular tumor enhancement, and intratumoral vascularization were associated with VHL mutations, while renal vein invasion was significantly associated with KDM5C and BAP1 mutations." (PMID 31901171, 2020). "Therefore, our results showed that ZMYND8 regulates the poised epigenetic state of these tumor-promoting genes by modulating their respective epigenetic regulators, KDM5C and EZH2." (PMID 33323928, 2020). "Therefore, our results indicate that ZMYND8 in association with the corepressor complex (KDM5C and EZH2) transcriptionally represses the poised tumor-promoting genes by removing H3K4Me3 and reinstating H3K27Me3 levels." (PMID 33323928, 2020). "Recent evidence suggests that KDM5C promotes tumor cells migration and invasion in breast cancer." (PMID 31060229, 2019). "Additionally, mutations of KDM5C and SETD2 were significantly associated with tumor size (p = 0.019 and p = 0.0445)." (PMID 26848523, 2016). "Histone demethylase activity of KDM5C was required in the function of VHL in tumor growth." (PMID 26848523, 2016). "HIF-1α has been reported to upregulate KDM5C, which mediates methylation of genes related to inflammation, stem cell differentiation, and hypoxia response, suggesting KDM5C’s potential involvement in the hypoxic tumor microenvironment and as a therapeutic target." (PMID 40450300, 2025). "KDM5C was selected for examination of its functional phenotype in GC tumorigenesis, and the results demonstrated that its overexpression could enhance tumor cell metastatic potential and promote xenograft tumor growth." (PMID 37202737, 2023). "The predictive value of KDM5C alterations were independent of tumor mutational burden and microsatellite status, suggesting that KDM5C alterations could be considered as a potential pan-cancer predictive biomarker for ICI treatment." (PMID 33953726, 2021). "To corroborate this hypothesis, we tested whether the heterozygous loss of Pax5 (Pax5-het), a common second hit identified in murine and human B-ALL-associated ETV6-RUNX1, would restrict the tumor cell type to B-ALL in Sca1-ETV6-RUNX1 mice, similarly to Kdm5c loss." (PMID 34336858, 2021). "Our model identified mutations in VHL (von Hippel-Lindau), PBMR1, BAP1, MTOR, ATM, SETD2, KDM5C and PTEN (phosphatase and tensin homolog), as well as copy number changes in MLH1, DUSP1 and RANDBP17 as significantly associated with various TF activity changes across tumours." (PMID 28139702, 2017). "We also disrupted the H3K4me3 demethylase Kdm5c to investigate the role of H3K4me3 in AML cell proliferation, which showed tumor suppressor activity in our CRISPR assays." (PMID 40341256, 2025). "We also note that the majority of ccRCC tumours with the Y chromosome loss gene expression signature do not harbour KDM5C mutations, arguing that there might be other mutations or cellular states that cooperate with the loss of the Y chromosome to permit or promote tumour evolution." (PMID 39955388, 2025). "Another histone demethylase, lysine demethylase 5C (KDM5C), which specifically demethylates H3K4, exhibits context-dependent oncogenic or tumor suppressor roles." (PMID 40867514, 2025). "To confirm the synergistic effect of KDM5C and YY1 on tumorigenicity and cancer cell proliferation, we analyzed the cell cycle progression and apoptosis rate of tumor cells in which KDM5C, YY1 or both had been depleted." (PMID 39433896, 2024).